LINC01127 (long independently transcribed non-coding RNA 1127)
Gene: Long non-coding RNA gene on chromosome 2 (101,961,596 to 101,989,015, forward strand). Ensembl gene ENSG00000281162.
Diseases named in the same sentence as LINC01127 in open-access papers:
LINC01127 is named in the same sentence as 4 diseases in open-access papers, as found by Europe PMC text mining. Sharing a sentence is not in itself a finding about the gene and the disease. The quoted sentences say what the papers report.
COVID-19 (1 paper, 2021). A disease caused by infection with severe acute respiratory syndrome coronavirus 2. "It has been observed that increased level of LINC02207, LINC01127 was associated with the severe COVID-19 group, whereas LINC02084, LINC02446, LINC00861, LINC01871, and ANKRD44-AS1 were associated with the mild COVID-19 group." (PMID 34940755, 2021).
glioblastoma (1 paper, 2025). The most malignant astrocytic tumor (WHO grade IV). "In glioblastoma (GBM), lactylation of histone H3 increases the expression of LINC01127, which directs polymerase II (POLR2A) to the mitogen-activated protein kinase kinase kinase kinase 4 (MAP4K4) promoter region." (PMID 40584966, 2025).
LINC01127 also shares sentences with these, for which no sentence is quoted: bladder cancer (1 paper); infection (1).